PDK1 (pyruvate dehydrogenase kinase 1)
Diseases named in the same sentence as PDK1 in open-access papers (continued):
Sharing a sentence is not in itself a finding about the gene and the disease.
breast cancer (continued). "Isogenic metastatic (4T1) and non-metastatic (67NR) breast cancer cell lines were characterized for their metabolic and acidosis features, including LDH-A/PDK-1 expression, glucose consumption, extracellular acidification rate (ECAR) and oxygen consumption rate (OCR)." (PMID 40551171, 2025). "The results showed that the mRNA level of HIF-1α did not change significantly between breast cancer cell groups, indicating that the regulation of HIF-1α by PDK1 may be transcriptionally independent." (PMID 38560503, 2024). "Although EGFR was suggested to be one of upstream regulators of PDK-1/AKT and Stat3 pathways, the role of EGFR activation plays in relation to PDK-1/AKT/mTOR/p70S6K/S6 cascade in breast cancers has not been firmly established." (PMID 16288304, 2005). "In addition to these, OSU-03012, a derivative of celecoxib, a cyclooxygenase-2 (COX2) inhibitor, which accounts for PDK1 but not COX2 inhibition, managed to sensitize breast cancer cell lines to tamoxifen therapy independently of their ER status and the ER downstream pathway." (PMID 29064423, 2017).
ovarian carcinoma (52 papers, 2008 to 2025). A malignant neoplasm originating from the surface ovarian epithelium. "Since we observed allele-dependent regulation of PDK1 in ovarian cancer cells, we examined the expression of PDK1 in patient samples in the Oncomine datasets." (PMID 34298795, 2021). "Further multivariate logistic regression analysis revealed that tumor size (P = 0.002) and extraovarian metastases status (P < 0.0001) were independent risk factors for the expression of PDK1 in ovarian cancer." (PMID 33403023, 2021). "The clinical relevance of PDK1 in metastasis was further supported by its correlations with DEGs associated with metastasis in TCGA data sets of ovarian cancer patients." (PMID 32071289, 2020). "Additionally, PDK1 is negatively correlated with CD8+ T-cell infiltration in ovarian cancer, andPDK1 knockdown is linked to improved CD8+ T-cell function and survival in tumor-bearing mice." (PMID 39578715, 2024). "We found PDK1 was an independent risk factor affecting metastasis of ovarian cancer, and could be useful in ovarian cancer risk assessment and future therapeutic targeting." (PMID 33403023, 2021). "To this end, we silenced PDK1 by lentiviral vector delivery of shRNA and investigated by digital pathology and microarray analysis morphologic and transcriptomic changes caused by this modulation in ovarian cancer xenografts." (PMID 33562444, 2021). "Among the four PDK isoforms (PDK1–4), PDK1 has been shown to be overexpressed in several cancers, including ovarian cancer, gastric cancer, colorectal cancer, prostate cancer, and acute myeloid leukemia." (PMID 40971960, 2025). "Previous studies have reported that PDK1 is highly expressed in ovarian cancer and acts as an oncogene in ovarian cancer via diverse mechanisms." (PMID 39578715, 2024). "This study aims to explore the potential role and regulatory mechanism of PDK1 in epithelial ovarian cancer (EOC)." (PMID 39578715, 2024). "For example, PDK1 facilitates ovarian cancer cell migration, invasion, and angiogenesis by regulating α5β1 integrins and activating JNK/IL-8 signaling." (PMID 39578715, 2024). "We also found that PDK1 expression decreased significantly, and cell senescence increased in S1PR1-deficient ovarian cancer cells." (PMID 37828220, 2023). "Platinum-resistant ovarian cancer cells exhibit increased levels of pyruvate dehydrogenase kinase 1 (PDK1) in comparison to platinum-sensitive cells." (PMID 37681030, 2023). "Reduced angiogenesis and increased necrosis in the OC316 and OVCAR3 tumor model were observed as the primary effect of PDK1 silencing in ovarian cancer." (PMID 37277821, 2023). "We have previously demonstrated that COL11A1 confers chemoresistance to ovarian cancer cells through the activation and phosphorylation of Akt and phosphoinositide-dependent kinase-1 (PDK1) stabilization." (PMID 37386587, 2023). "Increased levels of PDK1 have been reported in 45% of patients with acute myeloid leukemia, and a role for PDK1 in ovarian cancer progression has also been proposed." (PMID 35903683, 2022). "It has been reported that PDK1 enhances EMT to contribute to the cisplatin resistance of ovarian cancer." (PMID 35892859, 2022). "One previous study revealed that PDK1 silencing induces apoptosis and overcomes cisplatin resistance in ovarian cancer-resistant cells by downregulating the EGFR activation pathway." (PMID 36474273, 2022). "In parallel, TRPM7 silencing decreased the glucose uptake of tumor-bearing mice and TRPM7 levels were negatively correlated with IDH3B and UQCRC1, but positively with HK2 and PDK1 expression in ovarian cancer tissues." (PMID 35101076, 2022). "In the present study, we profiled the expression status of PDK1 in the ovarian cancer and evaluated the prognostic significance of PDK1 in metastasis of ovarian cancer." (PMID 33403023, 2021). "In the context of ovarian cancer, a recent study investigated effects of PDK1 silencing on cell motility and resistance to cisplatin." (PMID 33562444, 2021).
ovarian carcinoma (continued). "We used a variety of in vitro experiments to explore the influence of PDK1 on proliferation, invasion, migration, colony formation, apoptosis and the cell cycle of ovarian cancer cell lines CAOV3 and SKOV3." (PMID 33403023, 2021). "Just because PDK1 was obviously overexpressed in ovarian cancer, then we further investigated the effects of PDK1 on the ability of ovarian cancer cell growth and anchorage-independent growth." (PMID 33403023, 2021). "In this study, we found that PDK1 was highly expressed in ovarian cancer cell lines, and the results were verified in ovarian cancer tissues." (PMID 33403023, 2021). "Pyruvate dehydrogenase kinase 1 (PDK1) promotes ovarian cancer cell angiogenesis, invasion, and metastasis through α5β1 integrin and JNK/CXCL8 signaling." (PMID 35011369, 2021). "We found that the positive rate of CA125 (84.09%) and the PDK1's (82.95%) in ovarian cancer patients was almost equal." (PMID 33403023, 2021). "Our research shows that PDK1 is the only biological target that can independently predict the prognosis of ovarian cancer among various factors affecting ovarian cancer." (PMID 33403023, 2021). "In order to further confirm the fact that PDK1 is highly expressed in cancer tissues, we detected the expression and cellular distribution of PDK1 in the paraffin sections of 88 ovarian cancers and 46 benign ovarian tumors through IHC staining." (PMID 33403023, 2021). "Our team identified the expression of PDK1 in ovarian cancer cell lines and tissues through RT-PCR and immunohistochemical staining and evaluated the correlation of PDK1 expression with clinicopathologic features of patients and survival analyses." (PMID 33403023, 2021). "This up-regulation of PDK1 in ovarian tumour tissues suggests a potential role of PDK1 in ovarian cancer." (PMID 34298795, 2021). "In drug-resistant ovarian cancer cells, PDK1 expression was significantly upregulated, and knocking down PDK1 expression significantly increased cisplatin sensitivity." (PMID 34250022, 2021). "To be specific, we measured the percentage of tumor cells in different cell cycle stages including G0/G1, S and G2/M and evaluated the effect of PDK1 knockdown on the cell apoptosis in ovarian cancer cells by flow cytometry." (PMID 33403023, 2021). "Downregulation of PDK1 suppressed the biological behavior of ovarian cancer cells due to S phase arrest and cellular apoptosis." (PMID 33403023, 2021). "A recent study demonstrated PDK1 contributes to cisplatin resistance of ovarian cancer through EGFR activation and promotes epithelial–mesenchymal transition." (PMID 32071289, 2020). "In this study, we demonstrated upregulation of the gatekeeping enzyme, PDK1, in ovarian cancer patients, with significantly higher expression in metastatic foci." (PMID 32071289, 2020). "Immunoreactivity to PDK1 was significantly higher in ovarian cancers than benign cystadenomas (P < 0.001)." (PMID 32071289, 2020). "Our results additionally showed that PDK1 phosphorylates/inactivates PDHE1 leading to increased lactate production in ovarian cancer cells." (PMID 32071289, 2020). "Our findings suggest that PDK1, which is regulated by the tumor microenvironment, controls lactate production and promotes ovarian cancer cell metastasis via modulation of α5β1 integrin and JNK/IL-8 signaling." (PMID 32071289, 2020). "PDK1 staining was moderate-to-strong in ovarian cancers, in contrast to barely detectable staining in benign cystadenomas (upper)." (PMID 32071289, 2020). "This induction was impeded by blockage of IL-8 and CXCR1, suggesting that CAFs secrete chemokines, such as IL-8, which, in turn, enhance PDK1 expression in ovarian cancer cells through CXCR1." (PMID 32071289, 2020). "Our results demonstrate that OCM induces PDK1, which, in turn, contributes to ovarian cancer migration, invasion, and angiogenesis, thus metastasis." (PMID 32071289, 2020).
ovarian carcinoma (continued). "Silencing of PDK1 retarded lactate production, ovarian cancer cell adhesion, migration, invasion, and angiogenesis, and consequently metastasis, concomitant with decreased α5β1 integrin expression." (PMID 32071289, 2020). "The effects of conditioned medium derived from ovarian cancer-associated fibroblasts (CAF-CM) and omentum (OCM) on PDK1 expression were also assessed." (PMID 32071289, 2020). "PDK1 was overexpressed in the highly glycolytic human ovarian cancer cell line OC316 compared with the less glycolytic cell line IGROV-121." (PMID 32071289, 2020). "Significantly higher PDK1 expression in metastatic foci was detected, indicative of its potential contribution to ovarian cancer metastasis." (PMID 32071289, 2020). "In this study, we focused on the clinical significance, functional roles, and downstream mechanisms of PDK1 in ovarian cancer." (PMID 32071289, 2020). "To clarify the mechanistic pathways by which PDK1 regulates ovarian cancer metastasis, we screened lysates from OVCAR-3 cells with or without stable PDK1 overexpression." (PMID 32071289, 2020). "Our previous report indicated that chemoresistance in ovarian cancer cells develops through activation of the Akt/c/EBPβ pathway in concert with increased degradation of PDK1." (PMID 30975980, 2019). "Collagen I has been shown to promote MAPK activation in hepatocellular carcinoma cells, and to promote chemoresistance in ovarian cancer cells through the activation of Akt and pyruvate dehydrogenase kinase 1 (PDK1)." (PMID 30487436, 2018). "Pyruvate dehydrogenase kinase 1 (PDK1) is overexpressed in ovarian cancer and thus is a promising anticancer therapeutic target." (PMID 28617852, 2017). "The importance of PDK1 in ovarian cancer is underscored by an immunohistological analysis of the expression of the peroxisome proliferator-activated receptor β (PPARβ) and PDK1 in healthy ovary tissue, benign tumours and many malignant subtypes." (PMID 29064423, 2017). "We also observed that phosphorylated Akt levels in chemoresistant ovarian cancer cells were increased by COL11A1 via increased binding activity between PDK1 and COL11A1." (PMID 26087191, 2015). "The apparent increase in PDK1 expression in high-grade ovarian carcinomas is consistent with our previously reported parallel increase in ILK expression with increasing grade of ovarian carcinomas." (PMID 18349831, 2008). "All borderline and malignant ovarian tumours showed positive cytoplasmic and membrane PDK1 staining." (PMID 18349831, 2008). "In ovarian cancer, the expression of PDK1 and PDK4 were relatively low compared to PDK2, so we haven’t further explored whether they can phosphorylate FOXK2." (PMID 38734828, 2024). "Moreover, PDK1 has also been revealed as an outstanding predictor of ovarian cancer prognosis, and patients with high PDK1 expression have a reduced overall survival rate." (PMID 39578715, 2024). "However, the pathway through which PDK1 participates in ovarian cancer senescence regulation requires further investigation." (PMID 37828220, 2023). "PDK1 is upregulated by HIF1α through the HIF1α-RTK pathway in ovarian cancer." (PMID 37277821, 2023). "The schematic diagram of the molecular mechanism shows that, when S1PR1 is activated by S1P or a related agonist in ovarian cancer cells, PDK1 expression is increased, LATS1/2 expression is inhibited, and YAP expression is increased, thereby inhibiting ovarian cancer cell senescence." (PMID 37828220, 2023). "Overexpression of PDK1 inverted the function of miR-634 on cisplatin sensitivity of ovarian cancer." (PMID 38152652, 2023). "Another report from us has revealed that COL11A1 could increase phosphorylated Akt in chemoresistant ovarian cancer cells by stabilizing PDK1 protein." (PMID 35847935, 2022). "Thus, metformin treatment can sensitize chemoresistant ovarian cancer cells to cisplatin via the PDK1/HKII pathway, suggesting a potential role of metformin in improving ovarian cancer sensitivity to cisplatin." (PMID 36361682, 2022).
ovarian carcinoma (continued). "Siu and colleagues found the expression of PDK1 was high in ovarian cancer." (PMID 35961973, 2022). "After multivariate analysis, PDK1 was the only biological target that could independently predict the prognosis of ovarian cancer patients, which was consistent with the results of previous influencing factors of PDK1." (PMID 33403023, 2021). "PDK1 was highly expressed in ovarian cancer cell lines and OC tissues." (PMID 33403023, 2021). "PDK1 may serve as a novel prognostic biomarker, even a promising antineoplastic target of ovarian cancer." (PMID 33403023, 2021). "Moreover, in this study, we developed a new predictive indicator system using integration of serum CA125 level into the PDK1 expression of ovarian cancer." (PMID 33403023, 2021). "Together with previous studies, our current experiments demonstrated that PDK1 may participate in promoting the proliferation, invasion and metastasis of ovarian cancer cells." (PMID 33403023, 2021). "We further employed flow cytometry to analyze the effects of PDK1 on ovarian cancer cell apoptosis." (PMID 33403023, 2021). "It implied that PDK1 plays a critical role in the independent growth of ovarian cancer cells." (PMID 33403023, 2021). "Moreover, PDK1 was a superior predictor in prognosis of ovarian cancer and the incorporation of CA125 into PDK1 generated a predictive combination that displayed better predictive accuracy for overall survival." (PMID 33403023, 2021). "Speculatively, some intrinsic features of the cell lines used could account for differences observed after PDK1 silencing and our findings would certainly be strengthened by testing additional ovarian cancer cell line models." (PMID 33562444, 2021). "Michelle K. Y's team had confirmed that PDK1 could promote the development of ovarian cancer especially in metastasis by modulating tumor-mesothelial adhesion, invasion, and angiogenesis via α5β1 integrin and JNK/IL-8 signaling." (PMID 33403023, 2021). "From these results, we can deduce PDK1 may play a critical role in regulating biological behavior of ovarian cancer cells." (PMID 33403023, 2021). "In our experiments, knockdown of PDK1 reduced ovarian cancer cell adhesion to fibronectin and mesothelial cells along with downregulation of α5 integrin and β1 integrin, whereas ectopic overexpression exerted the opposite effects, supporting a role of PDK1 in the early steps of metastasis." (PMID 32071289, 2020). "Similar to Metascape analysis, “epithelial-mesenchymal transition (EMT) includes wound healing, fibrosis, and metastasis”, and “hypoxia” were within the top three significantly enriched gene sets identified, further supporting the theory that PDK1 drives ovarian cancer metastasis." (PMID 32071289, 2020). "In conclusion, we detected significant overexpression of PDK1 in ovarian cancer." (PMID 32071289, 2020). "In our investigation, transient knockdown of α5 or β1 integrin abolished PDK1-mediated ovarian cancer cell adhesion to fibronectin and mesothelial cells, clearly suggesting that cell adhesion to fibronectin and mesothelial cells induced by PDK1 is α5β1 integrin-dependent." (PMID 32071289, 2020). "We further evaluated the effects of PDK1 on ovarian cancer cell growth." (PMID 32071289, 2020). "Next, we examined the cell metabolic effects of PDK1 on ovarian cancer." (PMID 32071289, 2020). "Taken together, our results support a crucial role of PDK1 in ovarian cancer metastasis." (PMID 32071289, 2020). "Importantly, p85β-overexpressing ovarian cancer cells demonstrated coordinated enhanced phosphorylation of PDK1, SGK3, and NDRG1." (PMID 32385243, 2020). "In view of the significantly higher PDK1 immunoreactivity in metastatic foci compared with their corresponding primary carcinomas, we evaluated the effects of PDK1 on ovarian cancer cell adhesion to fibronectin and mesothelial cells via the cell-adhesion assay." (PMID 32071289, 2020).